IL6 (interleukin 6)
Diseases named in the same sentence as IL6 in open-access papers (continued):
Sharing a sentence is not in itself a finding about the gene and the disease.
End Stage Liver Disease (10 papers, 2019 to 2025). Final stage of a liver disease when the liver failure is irreversible and LIVER TRANSPLANTATION is needed. "It was reported that in patients with end-stage liver disease, the body’s immune system and inflammatory response were over-activated with a large number of inflammatory factors being released into the bloodstream (e.g., IL-6, IL-8, TNF-α, etc.), which caused damage to hepatocytes." (PMID 32938405, 2020). "Another study that retrospectively evaluated patients with end-stage liver disease showed IL6 values have a similar predictive value of 90-day and 1-year mortality with MELD score." (PMID 34080071, 2021). "As the intraperitoneal accumulation of IL-6 is commonly increased after inflammatory stimuli, IL-6ascites seems to be a promising marker of infectious diseases in patients with end-stage liver disease." (PMID 32899730, 2020).
enterocolitis (10 papers, 2017 to 2026). An inflammatory process affecting the small intestine and colon. "IL-6 was primarily elevated in dermatologic (n = 6, P = 0.0003), enterocolitis (n = 3, P = 0.01), and endocrine (n = 5, P = 0.03) irAEs." (PMID 39403935, 2024). "In a different study using IL-10−/− mice, which develop spontaneous enterocolitis, researchers found that female mice had a shorter colon length and greater levels of IL6 and TGFβ in the colon compared to males." (PMID 38255320, 2024). "Studies found that the increasing abundance of Oscillibacter had a positive correlation with inflammatory cytokines like IL-6 and INF-γ in mice suffering from enterocolitis, indicating Oscillibacter may serve as a potential gut inflammation marker at high altitudes." (PMID 40257273, 2025).
esophageal tumors (10 papers, 2012 to 2025). "We previously reported that IL-6-mediated induction of MDSCs was associated with esophageal tumor promotion and poor prognosis, and the NLR was related to the IL-6 and MDSC level." (PMID 34578883, 2021). "Using an esophageal tumor animal model, the authors confirmed that MDSC recruitment was associated with invasive esophageal tumors and increased IL-6 levels." (PMID 33390169, 2021). "In 2000, Iizuka investigated the anticancer and anticachectic effects of Coptidis rhizoma (CR) in nude mice with esophageal tumors that constitutively secreted interleukin-6 (IL-6) and caused cachexia." (PMID 31950049, 2019). "We used ELISAs to measure the circulating levels of IL-6 in the 4-NQO-induced esophageal tumor mouse model." (PMID 25238263, 2014). "To further investigate the potential correlation of IL-6 levels with esophageal tumor progression, we examined the levels of IL-6 in the PB samples from the 50 SCC patients and 12 healthy controls using ELISA." (PMID 25238263, 2014). "In the present study, the animal model provides the direct evidence on the link between IL-6, MDSCs accumulation and esophageal tumor formation." (PMID 25238263, 2014). "The mice that had esophageal tumors with invasive carcinoma had significantly higher serum IL-6 levels than those with hyperplasia or papilloma alone." (PMID 25238263, 2014). "In a 4-NQO-induced esophageal tumor animal model, MDSC recruitment was associated with invasive esophageal tumors and with increased IL-6 levels." (PMID 25238263, 2014). "It has also been observed that IL-6 expression is elevated (increases in both mRNA and protein concentrations) in esophageal tumor tissues; serum levels of IL-6 have also been correlated with tumor volume." (PMID 22917173, 2012). "There is a published report that described elevated IL-6 level in the esophagus tumor tissue of a 51-year-old male patient, suggesting that IL-6 may have a role in esophagus tumor development." (PMID 31572184, 2019). "The C57 mice with IL-6 stimulation showed significantly increased MDSC levels, which was associated with a higher SUVR in the esophageal lesions and an increased incidence of invasive esophageal tumor formation." (PMID 25238263, 2014). "Since IL6 overexpression is only observed in ESCC samples, while BCL3 higher mRNA levels are detected both in tumor-surrounding mucosa and esophageal tumors, paracrine IL6 signaling could be responsible for BCL3 induction in tumor-adjacent tissue." (PMID 34422669, 2021). "Moreover, we evaluated the relationship between MDSC recruitment, IL-6 levels, and tumor progression by adding 4-nitroquinoline 1-oxide (4-NQO) to the drinking water of mice to induce esophageal tumors." (PMID 25238263, 2014). "The role of IL-6 in MDSC accumulation and tumor progression was further examined using the 4-NQO-induced esophageal tumor model in the presence or absence of IL-6." (PMID 25238263, 2014). "To assess this hypothesis, we evaluated the relationship between IL-6 and circulating MDSC subsets in patients, and the ability of IL-6 to stimulate MDSC accumulation in 4-NQO-induced esophageal tumor model to provide new insights into the development of immune-based therapy." (PMID 25238263, 2014).
esophagitis (10 papers, 2010 to 2025). An acute or chronic inflammatory disease affecting the esophageal wall. "This pleiotropic cytokine is an upstream mediator for IL-6 and TNFα in GERD-associated esophagitis, which in turn drive disease progression." (PMID 35565378, 2022). "Several studies have shown that IL-1β, present in esophagitis, induces IL-6 production, driving inflammation." (PMID 35565378, 2022). "This cytotoxicity of hydrogen peroxide seemed to be related with its ability to induce IL-1β, IL-8, and IL-6, suggesting a role for classic stress signaling pathways during esophagitis and GERD." (PMID 25276052, 2014). "Exposure to components of the gastric refluxate is sufficient to stimulate esophageal cells to release a pro-inflammatory cytokine, IL-6, with the potential to mediate the esophageal motor abnormalities associated with GERD-induced esophagitis." (PMID 22277344, 2012). "Esophagitis was diagnosed in three of the four patients (21.4%) with increased IL-6." (PMID 40843700, 2025). "We found that rs1800795 in IL6 resulted in a 2.16-fold increase in esophagitis." (PMID 20811626, 2010). "Proinflammatory cytokines, IL-1ß, IL-6 and TNF-α are key players in signaling pathways such as NF-κB activation and mitogen activated protein kinase (MAPK) cascade initiation and appear to play important roles in esophageal diseases including RE." (PMID 32408627, 2020).
Fabry disease (10 papers, 2009 to 2025). Fabry disease (FD) is a progressive, inherited, multisystemic lysosomal storage disease characterized by specific neurological, cutaneous, renal, cardiovascular, cochleo-vestibular and cerebrovascular manifestations. "Elevated expression levels of inflammatory cytokines, such as IL-1β or IL-6, are associated with the disease burden and clinical phenotype of Fabry disease." (PMID 41000387, 2025). "Small-vessel disease in Fabry's disease is associated with white-matter changes and evidence suggests that the extent of such lesions is influenced by gene polymorphisms as interleukin 6, endothelial nitric oxide synthase, factor V, and protein Z." (PMID 19895675, 2009). "Serum, plasma, PBMCs, and several of the immune cells that include MOs, DCs, and NK cells have shown massive production of pro-inflammatory cytokines (e.g., IFNγ, TNF α, IL1β, and IL6) in patients with Fabry disease." (PMID 37189685, 2023). "Patients with Fabry disease also demonstrate an increase in T cell subsets and increased circulatory levels of pro-inflammatory cytokines, such as TNFα, IFNγ, IL1α, IL1β, IL6, and IL17." (PMID 39596318, 2024). "Elevated levels of IL-6 and TGF-β1 were also found in patients with Fabry disease, suggesting that chronic inflammation is a driver of organ damage in Fabry disease." (PMID 41000387, 2025). "There was a trend for low serum levels of IL-6 and high serum levels of TNF-α and high-sensitive CRP in Fabry patients; plasma concentrations of soluble VCAM-1 were significantly higher in Fabry disease patients than in healthy volunteers (p = 0.02)." (PMID 24207059, 2013).
glucose metabolism disorders (10 papers, 2009 to 2024). "Elevated concentrations of CRP, IL-6, and TNF with suboptimal VD levels have been associated with an increased risk of cardiovascular events, glucose metabolism disorders, neurodegenerative diseases, and overall mortality." (PMID 37175418, 2023). "TNF-α and IL-6 levels have been reported by others to be increased in patients with OSA and in those with left ventricular diastolic dysfunction and glucose metabolism disorders." (PMID 21122092, 2010). "The relationship between elevated serum hs-CRP level and glucose metabolism disorders may be intermediated by increased secretion of TNF-α and IL-6." (PMID 28361994, 2017).
Hyperammonemia (10 papers, 2014 to 2025). An increased concentration of ammonia in the blood. "GABA‐ergic tone in the motor cortex was also found to be increased in minimal HE (Grades 1 and 2), and the GABAA antagonist bicuculline decreases IL‐6 and TNFα and increases IL‐10 in the plasma of chronic hyperammonemia rats." (PMID 41141377, 2025). "Several studies confirmed that hyperammonemia activates the secretion of inflammatory cytokines (interleukin-6 (IL-6), interleukin-1beta (IL-1β), interferon gamma (IFN-γ), and tumor necrosis factor α (TNFα) in ammonia-induced astrocyte cultures." (PMID 35624703, 2022). "The present review also includes data indicating that hyperammonemia is related to the release of a high level of pro-inflammatory factors, such as interleukin-6, by astrocytes." (PMID 33584185, 2021). "The results reported show that hyperammonemia induces activation of astrocytes and microglia in the hippocampus, increasing the levels of pro-inflammatory cytokines IL-1β and IL-6." (PMID 26883214, 2016). "The results reported show that hyperammonemia induces astrocytes and microglia activation in the hippocampus, increasing pro-inflammatory cytokines IL-1β and IL-6." (PMID 26883214, 2016). "Hyperammonemia was similar before and after resolution of inflammation in patients.There was a significant decrease in the white blood cell count, nitrate/nitrite, IL-6, IL-1β, and TNF-α by infection treatment.Induced hyperammonemia significantly worsened neuropsychological test scores." (PMID 34361075, 2021). "We have recently shown using the same animal model used here that hyperammonemia per se induces peripheral inflammation by increasing proinflammatory TNF-a, IL-6, and PGE2 and decreasing anti-inflammatory IL-10." (PMID 32087723, 2020). "Hyperammonemic rats showed increased levels of IL-6 (151 ± 15% of control, p < 0.05) in the plasma at 11 days of hyperammonemia but not thereafter." (PMID 34202516, 2021). "Hyperammonemia is also frequently complicated by systemic inflammation including increasing systemic and cerebral levels of vascular endothelial growth factor (VEGF), Tumor Necrosis Factor (TNF)-alpha and the interleukins (IL)-1beta and IL-6." (PMID 24433342, 2014).
Hyperkeratosis (10 papers, 2018 to 2025). Hyperkeratosis is a histopathological term defining a thickened stratum corneum and may be present in many different skin conditions, with many possible overlaps. "Specifically, the accumulation of keratinocytes in the ductal infundibulum causes hyperkeratosis and induces proinflammatory cytokines, including IL‐1, IL‐6 and TNF‐α, resulting in a closed or open comedones (Grade I)." (PMID 38426932, 2024). "IL-6 belongs to the gp130 family of cytokines and acts as a potent proinflammatory mediator, promoting hyperkeratosis of the pilosebaceous duct." (PMID 40851686, 2025). "In the present study, we also observed similar manifestations, such as increased skin redness, scaling, acanthosis, elongation of rete-like ridges, hyperkeratosis, increased levels of IL-6 and IL-17A, and acanthosis." (PMID 37686332, 2023). "Skin histology revealed hyperkeratosis and acanthosis of the epidermis with predominantly neutrophilic infiltration, and immunohistochemical staining showed the activation of the IL-6-gp130-JAK-STAT axis in skin lesions." (PMID 35046931, 2021). "IL-6 increases the production of IgE, which induces mast cell degranulation, and induces Th2 maturation to induce inflammatory responses, such as eosinophil infiltration and epidermal hyperkeratosis." (PMID 35457288, 2022). "Taken together, these results imply that EEFR can suppress the production of TNF-α, IFN-γ, IL-6, and MCP-1, and thus, inhibit epidermal hyperplasia, hyperkeratosis, and immune cell infiltration." (PMID 37047066, 2023). "IL-1β and IL-6 have been confirmed to promote the differentiation of CD4+T cells into Th17 cells, in which IL-17 is produced, and higher IL-17 levels recognized by keratinocytes leads to severe hyperkeratosis and inflammatory infiltration." (PMID 37111171, 2023). "Collectively, these findings suggest that EESP can suppress the production of TNF-α, IFN-γ, IL-6, and MCP-1 and consequently inhibit epidermal hyperplasia, hyperkeratosis, and immune cell infiltration, which ameliorate the skin symptoms of CD and suppress skin-thickening." (PMID 37686078, 2023).
hyperparathyroidism (10 papers, 2014 to 2025). Hyperfunction of the parathyroid glands resulting in the overproduction of parathyroid hormone. "Increased levels of proinflammatory cytokines like IL-1 beta and IL-6 are primarily implicated in the development of acquired relative hyperparathyroidism by upregulating calcium-sensing receptors on parathyroid cells." (PMID 35663648, 2022). "In this context, patients with hyperparathyroidism will, theoretically, have higher levels of IL-6, CRP, or tumor necrosis factor-α (TNF-α)." (PMID 24782595, 2014). "Our previous study disclosed that incremental serum levels of serum IL-6 in parallel with iPTH elevation could be effectively suppressed by calcitriol therapy, which indicated that hyperparathyroidism may aggravate inflammation in patients on maintenance HD." (PMID 33218086, 2020). "Some showed elevated levels of these inflammatory markers in hyperparathyroidism, whereas others found that levels of CRP, IL-6, and leukocytes were similar in patients and controls." (PMID 24782595, 2014). "Although IL-6 is secreted from normal parathyroid tissue and with PTH in hyperparathyroidism, the negative correlation of IL-6 with PTH in our study can be explained by slight increases in Ca levels." (PMID 36161625, 2022).
immunotoxicity (10 papers, 2015 to 2025). "Moreover, PVC MP pose a very serious threat to the human organism, as they can circulate in the body and their long exposure can cause immunotoxicity to the cells stimulating the release of interleukin 6 (IL-6) and tumor necrosis factor-α (TNF-α)." (PMID 34069160, 2021). "In accordance, feeding AFB1-contaminated diets resulted in heightened expression of IL-6, IFN-γ, and IL-10; impaired lymphocyte; and delayed cell-mediated immune response, while Se deficiency aggravated AFB1-induced immunotoxicity." (PMID 38147231, 2024). "Recently, it was also reported that dibutyltin, another organotin compound that causes severe immunotoxicity and developmental toxicity in animals, increased iNOS, TNF-α, and IL-6 mRNA levels in BV-2 cells." (PMID 26221064, 2015). "A study showed that carbon nanotubes induce immunotoxicity, and quercetin can ameliorate its induced immunotoxicity, inflammation, and oxidative response through mechanisms such as decreasing TNF-α and IL6 concentrations, and mRNA levels." (PMID 39434897, 2024). "Similarly, Wang and colleagues reported that T-2 induced the overexpression of proinflammatory genes and upregulated the mRNA expression of TNFα, IL-1β, and IL-6, leading to the activation of the JAK-STAT signaling pathway contributing to immunotoxicity." (PMID 40864073, 2025).
intracranial aneurysms (10 papers, 2014 to 2024). "Evidence from a meta-analysis included six case-control studies, which included 1188 intracranial aneurysms cases and 4099 controls, suggested that IL-6 promoter polymorphisms (-174G/C and -572G/C) were associated with intracranial aneurysms." (PMID 26830841, 2016). "After rupture of the intracranial aneurysm, high CSF IL-6 levels were found to associate with vasospasm." (PMID 26176774, 2015). "In this study, we aimed to measure the IL-6 levels at the orifices of intracranial aneurysms and peripheral veins and to assess their associations with clinical neurological severity and outcome." (PMID 26176774, 2015). "The strength of our study was the direct measurement of IL-6 at the orifice of the intracranial aneurysm with simultaneous blood sample drawn from the peripheral vein to elucidate the association between circulating IL-6 levels and clinical outcome." (PMID 26176774, 2015). "The plasma level of IL-6 is an independent prognostic biomarker that could be used to aid in the identification of patients at high-risk of poor neurological outcome after rupture of the intracranial aneurysm." (PMID 26176774, 2015). "We aimed to explore the genetic overlap and associations between inflammation (IL6 signaling and CRP) and intracranial aneurysm (IA) risk." (PMID 34168680, 2021). "IL-6 has also been investigated in the context of intracranial aneurysms." (PMID 30988354, 2019). "We hypothesized that the plasma level of IL-6 could be an independent biomarker in predicting clinical outcome of patients with ruptured intracranial aneurysm." (PMID 26176774, 2015). "Similar to the implication of the CSF IL-6 level, our results showed that plasma levels of IL-6 could be valuable outcome predictors in patients with rupture of the intracranial aneurysm." (PMID 26176774, 2015).
kidney transplant (10 papers, 2014 to 2025). A surgical procedure in which one or both kidneys from a donor are implanted into a recipient. "Anti-IL6 therapies for the management of treatment-naïve or treatment-resistant antibody-mediated kidney transplant rejection episodes." (PMID 40357502, 2025). "This study aimed to evaluate the levels of FGF23, Klotho, IL-6, IL-10, and Mstn in relation to subjects without comorbidities in stable kidney transplant recipients receiving triple immunosuppressive therapy." (PMID 41303166, 2025).
Left ventricular diastolic dysfunction (10 papers, 2009 to 2024). Abnormal function of the left ventricule during left ventricular relaxation and filling. "Clinical studies have shown that serum levels of IL-17 and IL-6 are significantly increased in patients with left ventricular diastolic dysfunction." (PMID 39502194, 2024). "Furthermore, logistic regression analysis indicated that the combined elevation of IL-17 and IL-6 is an independent predictor of poor prognosis in left ventricular diastolic dysfunction." (PMID 39502194, 2024). "Regardless of sex, hypertensive patients with the second stage of the left ventricular diastolic dysfunction have significantly higher (compared to the first stage) systemic blood concentrations of C-reactive protein, tumor necrosis factor alpha, and interleukin-6." (PMID 35997392, 2022). "Increased IL-6 or the activation of IL-6 signaling has been reported to contribute to the development of left ventricular diastolic dysfunction in rats or mice, which may be partly explained by the IL-6-induced inhibition of SR function observed in adult rat ventricular cardiomyocytes." (PMID 34975847, 2021). "In particular increased plasma levels TNF-α and IL-6 seem to be correlated with impaired LVDD and more advanced left ventricular diastolic dysfunction." (PMID 19909503, 2009).